PPIA (peptidylprolyl isomerase A)
Description:
Catalyzes the cis-trans isomerization of proline imidic peptide bonds in oligopeptides. Exerts a strong chemotactic effect on leukocytes partly through activation of one of its membrane receptors BSG/CD147, initiating a signaling cascade that culminates in MAPK/ERK activation. Activates endothelial cells (ECs) in a pro-inflammatory manner by stimulating activation of NF-kappa-B and ERK, JNK and p38 MAP-kinases and by inducing expression of adhesion molecules including SELE and VCAM1. Induces apoptosis in ECs by promoting the FOXO1-dependent expression of CCL2 and BCL2L11 which are involved in EC chemotaxis and apoptosis. In response to oxidative stress, initiates proapoptotic and antiapoptotic signaling in ECs via activation of NF-kappa-B and AKT1 and up-regulation of antiapoptotic protein BCL2. Negatively regulates MAP3K5/ASK1 kinase activity, autophosphorylation and oxidative stress-induced apoptosis mediated by MAP3K5/ASK1. Necessary for the assembly of TARDBP in heterogeneous nuclear ribonucleoprotein (hnRNP) complexes and regulates TARDBP binding to RNA UG repeats and TARDBP-dependent expression of HDAC6, ATG7 and VCP which are involved in clearance of protein aggregates. Plays an important role in platelet activation and aggregation (By similarity). Regulates calcium mobilization and integrin ITGA2B:ITGB3 bidirectional signaling via increased ROS production as well as by facilitating the interaction between integrin and the cell cytoskeleton (By similarity). Binds heparan sulfate glycosaminoglycans. Inhibits replication of influenza A virus (IAV). Inhibits ITCH/AIP4-mediated ubiquitination of matrix protein 1 (M1) of IAV by impairing the interaction of ITCH/AIP4 with M1, followed by the suppression of the nuclear export of M1, and finally reduction of the replication of IAV. (Microbial infection) May act as a mediator between human SARS coronavirus nucleoprotein and BSG/CD147 in the process of invasion of host cells by the virus. (Microbial infection) Stimulates RNA-binding ability of HCV NS5A in a peptidyl-prolyl cis-trans isomerase activity-dependent manner. (Microbial infection) May act as a receptor for M.genitalium adhesin protein P140 (also called MgPa).
Synonyms: CYPA; CYPH; HEL-S-69p
Tractability: Small molecule: a structure with a bound ligand is known; a high-quality ligand is known; it has a binding pocket of medium quality; it belongs to a druggable protein family. Antibody: UniProt places it where antibodies can reach, with high confidence; its Gene Ontology location is reachable by antibodies, with high confidence. PROTAC: UniProt records ubiquitination sites on it; ubiquitination databases record sites on it; its protein half-life has been measured; a small molecule that binds it is known. Other modalities: an approved drug acts on it.
Target class: Isomerase; Enzyme
Gene: Protein-coding gene on chromosome 7 (44,796,678 to 44,824,564, forward strand). Ensembl gene ENSG00000196262.
Subcellular location: Cytoplasm; Secreted; Nucleus; Cell membrane
Pathways (Reactome):
Disease: APOBEC3G mediated resistance to HIV-1 infection; Assembly Of The HIV Virion; Binding and entry of HIV virion; Budding and maturation of HIV virion; Early Phase of HIV Life Cycle; Integration of provirus; Minus-strand DNA synthesis; Plus-strand DNA synthesis; SARS-CoV-1 activates/modulates innate immune responses; Uncoating of the HIV Virion
Immune System: Calcineurin activates NFAT; Gene and protein expression by JAK-STAT signaling after Interleukin-12 stimulation; Neutrophil degranulation
Hemostasis: Basigin interactions; Platelet degranulation
Gene Ontology:
Molecular function: heparan sulfate binding; peptidyl-prolyl cis-trans isomerase activity; protein binding; RNA binding; cyclosporin A binding; integrin binding; virion binding
Biological process: activation of protein kinase B activity; apoptotic process; cell adhesion molecule production; cellular response to oxidative stress; endothelial cell activation; leukocyte chemotaxis; lipid droplet organization; negative regulation of oxidative stress-induced intrinsic apoptotic signaling pathway; negative regulation of protein K48-linked ubiquitination; negative regulation of protein kinase activity; negative regulation of protein phosphorylation; negative regulation of stress-activated MAPK cascade; negative regulation of viral life cycle; neutrophil chemotaxis; positive regulation of MAPK cascade; positive regulation of protein phosphorylation; positive regulation of protein secretion; positive regulation of viral genome replication; protein peptidyl-prolyl isomerization; regulation of apoptotic signaling pathway; regulation of viral genome replication; platelet activation; platelet aggregation; protein folding; viral release from host cell
Cellular component: cytoplasm; cytosol; extracellular exosome; extracellular region; focal adhesion; membrane; nucleus; plasma membrane; protein-containing complex; vesicle; ficolin-1-rich granule lumen; secretory granule lumen
Genetic constraint (gnomAD): Loss-of-function variants: 2 observed, 14.66 expected, observed/expected ratio (o/e) 0.14, 90% interval 0.055 to 0.43. The upper end of that interval is the gene's LOEUF score, 0.43, which puts it in group 1 of 6, group 1 being the genes least tolerant of losing a copy. Missense variants: 91 observed, 183.83 expected, observed/expected ratio (o/e) 0.5, 90% interval 0.42 to 0.59. Synonymous variants: 57 observed, 62.15 expected, observed/expected ratio (o/e) 0.92, 90% interval 0.74 to 1.14.
Homologues: Orthologues: chimpanzee PPIA (100% identical), zebrafish ppifa (76% identical), zebrafish ppiab (75% identical), zebrafish ppiaa (73% identical), Caenorhabditis elegans cyn-1 (72% identical), Caenorhabditis elegans cyn-7 (71% identical), Caenorhabditis elegans cyn-3 (70% identical), Caenorhabditis elegans cyn-2 (68% identical), Drosophila melanogaster Cyp40 (54% identical), Caenorhabditis elegans cyn-9 (53% identical), Drosophila melanogaster Moca-cyp (52% identical). Paralogues in human: PPIAL4C (86% identical), PPIAL4A (85% identical), PPIAL4E (84% identical), PPIAL4F (84% identical), PPIAL4G (84% identical), PPIAL4H (84% identical), PPIAL4D (84% identical), PPIF (76% identical), PPID (67% identical), PPIE (67% identical), PPIB (65% identical), PPIH (58% identical), and 10 more.
Diseases named in the same sentence as PPIA in open-access papers:
PPIA is named in the same sentence as 250 diseases in open-access papers, as found by Europe PMC text mining. Sharing a sentence is not in itself a finding about the gene and the disease. The quoted sentences say what the papers report.
HIV-1 infection (81 papers, 2006 to 2026). The type species of lentivirus and the etiologic agent of acquired immunodeficiency syndrome (AIDS). "Notably, previous studies have demonstrated that polymorphisms in the regulatory region of PPIA gene, which encodes CypA, influence susceptibility to HIV-1 infection or disease progression." (PMID 24663101, 2014). "CypA is encoded by the peptidyl prolyl isomerase A (PPIA) gene, and regulatory PPIA polymorphisms are a component of genetic susceptibility to HIV-1 infection or disease progression." (PMID 23322171, 2013). "One notable example is the insertion of cyclophilin A (PPIA) into TRIM5α in the owl monkey leading to a novel gene fusion that confers resistance to HIV-1 infection." (PMID 23497673, 2013). "For instance, knockout of previously known HIV-1 interactors Cyclin T1 (CCNT1), Peptidylprolyl isomerase A (CYPA) and Lens epithelium–derived growth factor (LEDGF) reduced susceptibility to HIV-1 infection of primary human CD4+ T cells to approximately 20 percent of wild-type T cells." (PMID 35892930, 2022).
viral infection (52 papers, 2007 to 2025). "The PPIA gene family encodes proteins with functions in immune responses, as well as resistance to cancer, autoimmune diseases, protozoan, and viral infections." (PMID 33003996, 2020). "Bai and coworkers demonstrated that viral infection induced an increase in the abundance of PPIA, which interacts and mediates protection from proteasomal degradation of PTK2." (PMID 35281454, 2022).
hepatocellular carcinoma (29 papers, 2008 to 2025). A malignant tumor that arises from hepatocytes. "PPIA has been reported to be upregulated in serval malignant tumors, like colorectal, pancreatic, lung, and hepatocellular carcinoma." (PMID 32153636, 2020). "Intriguingly, SNPs in the PPIA gene that destabilize CyPA can protect hepatocytes from HCV infection in cell culture, suggesting PPIA SNPs contribute to the observed heterogeneity of HCV permissiveness in hepatoma cell populations in vitro." (PMID 23852270, 2013). "In addition, highly expressed pseudogene PPIAP22 promotes hepatocellular carcinoma progression via up-regulating PPIA expression by acting as a ceRNA for miR-197-3p." (PMID 34660601, 2021). "Peptidylprolyl isomerase A (PPIA), a.k.a. as cyclophilin A, has been related with ERK1/2 phosphorylation and NF-κB activation, gastrin cancer serum biomarker and poor prognosis in hepatocellular carcinoma." (PMID 38252632, 2024).
breast carcinoma (27 papers, 2007 to 2026). "Charalampos G Kalodimos group have reported that PPIA binds to and enhances activation of CrkII, which stimulate breast cancer cell migration." (PMID 38830868, 2024). "PPIA along with ACTB was found to be the most stable reference gene for basal type breast cancer cell lines in hypoxic and serum deprived conditions." (PMID 34681026, 2021). "Interestingly, DepMap Cancer Gene Dependency data show that reduced viability (fitness) following PPIA/CYPA-KO is more commonly seen in breast cancer cell lines with reduced BRCA2 copy number." (PMID 38943005, 2024). "More recently, the presence of full-length recombinant proteins—alpha 1-antitrypsin (A1AT), triose-phosphate isomerase 1 (TPI1), peptidyl-prolyl cis-trans isomerase A (PPIA), and peroxiredoxin 2 (PRDX2)—as microarrays evaluated potential antigens associated with early-stage breast cancer tumors." (PMID 37887534, 2023). "In breast cancer, the PPIA/CrkII axis modulates host antitumor immune escape." (PMID 36231045, 2022). "In breast cancer, the pharmacological inhibition of PPIA may provide promising and unexpected results in cancer biology, in part by targeting the PPIA/CrkII axis that can modulate the host antitumor immune escape." (PMID 33790943, 2021). "Various other reference genes in the past have been described to be suitable reference genes in breast cancers including GAPDH, ACTB, PPIA and RNA28S/RNA18S." (PMID 34681026, 2021). "There is a marked difference in ADHFE1 expression among breast cancer cells, although overall expression levels of ADHFE1 are rather low compared to housekeeping genes PPIA and ACTB." (PMID 33916579, 2021). "The highest frequency of antibodies to an individual TAA in breast cancer was against A1AT (83.3%) and TPI1 (66.7%), followed by PPIA (58.3%) and PRDX2 (50%)." (PMID 33096879, 2020). "The authors examined by ELISA the presence of AAbs to five individual TAAs, PPIA, PRDX2, FKBP52, HSP-60, and MUC1, in sera from 60 breast carcinoma patients, 82 breast carcinoma in situ patients, and 93 healthy controls." (PMID 21423545, 2011). "Three of the five individual TAAs, FKBP52, PPIA, and PRDX2, showed significantly increased reactivity in breast carcinoma patients and breast carcinoma in situ patients compared to healthy controls." (PMID 21423545, 2011). "PPIA participates in the regulation of miRNA and impacts the sensitivity of breast cancer cells to doxorubicin and the knockdown of RUNX, which is involved in the YAP signaling pathway, enhances sensitivity to doxorubicin in breast cancer cells." (PMID 41375077, 2025).
atherosclerosis (26 papers, 2009 to 2025). A disease characterized by the build-up of fatty material and calcium deposition in the arterial wall resulting in partial or complete occlusion of the arterial lumen. "CyPA (PPIA) participates in atherosclerosis and thrombosis through inflammatory and oxidative stress-related pathways (such as NF-κB and MAPK pathways) and regulates the dynamic balance of intracellular Ca2+." (PMID 40305362, 2025). "Cyclophilin A (CyPA; encoded by PPIA) is a ubiquitously expressed protein secreted in response to inflammatory stimuli that stimulates vascular SMC migration and proliferation, endothelial cell adhesion molecule expression, and inflammatory cell chemotaxis, thereby promoting atherosclerosis." (PMID 35637715, 2022).
pancreatic cancer (24 papers, 2010 to 2024). "In this study we utilized highly purified recombinant PPIA to probe its extracellular activities on multiple cell lines that included both leukemic and pancreatic cancer cells." (PMID 22631225, 2012).
lung carcinoma (21 papers, 2010 to 2026). "Furthermore, PPIA is also upregulated in other solid tumors such as bladder, esophageal, renal, hepatocellular, and lung cancer and is associated with poor prognosis." (PMID 38956267, 2024). "Taken together, SFPQ is present on the cell surface and affects cell function via interaction with S100A4, PPIA, etc. in lung cancer and other solid cancer cells." (PMID 40770831, 2025). "In summary, our study provides actionable mechanistic insights about NRF2 stability and reveals PPIA as a promising target for treating NRF2-hyperactivated lung cancer." (PMID 38830868, 2024). "Notably, the expression levels of both PPIA and BSG were increased at advanced cancer stages in liver hepatocellular carcinoma and lung adenocarcinoma, indicating that the overexpression of CypA/CD147 may be associated with the poor prognosis of patients with liver or lung cancer." (PMID 36012604, 2022). "The proteins TXN and PPIA (Cyclophilin A) were up-regulated in lung cancer BALs as compared to the other groups." (PMID 23389041, 2013). "Whereas, other proteins, such as LPCAT2 that is highly expressed in inflammatory cells, BPIFA3 that is highly expressed in lung cancer, PPIA that activates NFkB pathway, and FABP4 that has pro-angiogenic role, were downregulated in SBP1 overexpression xenograft tumors." (PMID 25974208, 2015). "Cellular BSG has been shown to be cri-tical for PPIA-mediated phosphorylation of ERK1/2 in several other cell lines such as HeLa cells and lung cancer cells." (PMID 22631225, 2012).
glioma (19 papers, 2012 to 2025). A benign or malignant brain and spinal cord tumor that arises from glial cells (astrocytes, oligodendrocytes, ependymal cells). "Due to the profound impact on survival in glioma patients, 4 genes, namely IFNGR2, GLUD1, PPIA, and CASP8 were identified." (PMID 36466844, 2022). "The PPIA, H2AFZ, and HPRT1 genes have been proven to be the most stable reference genes in mouse oocytes and preimplantation-stage embryos under different culture conditions, while HPRT1 and RPL13A have been demonstrated to be the most stable reference genes in glioma stem cells (GSCs)." (PMID 37170359, 2022).
colorectal cancer (15 papers, 2010 to 2024). A primary or metastatic malignant neoplasm that affects the colon or rectum. "As the results of transcriptional analysis depend on genes used as normalizers, we used several internal controls, namely the most popular (GAPDH), the pair of genes previously found to be stably expressed in colorectal cancer (PPIA and RPLP0), and RN18S1, which all yielded consistent results." (PMID 34884259, 2021).
gastric cancer (15 papers, 2010 to 2024). A primary or metastatic malignant neoplasm involving the stomach. "Elevation of PPIA expression has been observed in some solid cancers, such as non-small cell lung carcinoma and gastric cancer." (PMID 26752561, 2016).
non-small cell lung carcinoma (11 papers, 2012 to 2024). A group of at least three distinct histological types of lung cancer, including non-small cell squamous cell carcinoma, adenocarcinoma, and large cell carcinoma. "Moreover, increased expression of PPIA leads to chemotherapy resistance in multiple cancers and RNA interference (RNAi) of PPIA in a non-small cell lung cancer model slowed tumor growth, thereby suggesting a causative role in cancer progression." (PMID 22631225, 2012).
Sepsis (11 papers, 2013 to 2025). Sepsis is defined as life-threatening organ dysfunction caused by a dysregulated host response to infection. "Key genes we identified, such as RPL10, MYL12B, and PPIA, have been shown to play significant roles in the mechanisms associated with sepsis and AKI." (PMID 40428155, 2025).
lung adenocarcinoma (10 papers, 2019 to 2024). A carcinoma that arises from the lung and is characterized by the presence of malignant glandular epithelial cells. "Studies have confirmed that the upregulation of PPIA is associated with a poor OS in diseases such as lung adenocarcinoma." (PMID 35840882, 2022). "In lung adenocarcinoma, the expression levels of PPIA and BSG gradually increased until cancer stage 3, but there was no further increase in cancer stage 4." (PMID 36012604, 2022). "By differential expression analysis and LASSO logistic regression analysis we constructed an 8-gene (IKBKB, LTBR, MIF, PPARD, PPIA, PSME3, S100A6, SEMA4B) based risk score model to predict lymph node metastasis in lung adenocarcinoma." (PMID 34109216, 2021). "The PPIA expression level also implied the clinical characteristics of resected lung adenocarcinomas and was correlated with a poor prognosis of lung adenocarcinoma.However, the in-depth study of the PPIA overexpression mechanism in CRC was insufficient." (PMID 32153636, 2020). "The higher the expression of PPIA, the worse the survival in bladder carcinoma, esophageal carcinoma, kidney chromophobe, liver hepatocellular carcinoma, lung adenocarcinoma, pancreatic adenocarcinoma, sarcoma, skin cutaneous melanoma, and stomach adenocarcinoma." (PMID 36012604, 2022). "However, lung adenocarcinoma showed a similar expression pattern of between PPIA and BSG in all cancer stages, indicating that targeting CypA/CD147 interactions may be more effective for the treatment of lung adenocarcinoma than lung squamous cell carcinoma." (PMID 36012604, 2022). "Interestingly, the expression levels of PPIA and BSG in lung squamous cell carcinoma did not affect patient survival, whereas the overexpression of PPIA and BSG decreased survival of patients with lung adenocarcinoma." (PMID 36012604, 2022).
cholangiocarcinoma (8 papers, 2011 to 2024). A carcinoma that arises from the intrahepatic biliary tree (intrahepatic cholangiocarcinoma) or from the junction, or adjacent to the junction, of the right and left hepatic ducts (hilar cholangiocarcinoma). "Among the 24 tumor types, PPIA expression is markedly higher in cholangiocarcinoma, esophageal carcinoma, and uterine corpus endometrial carcinoma than in normal tissues." (PMID 36012604, 2022).
multiple myeloma (8 papers, 2021 to 2026). "In refractory multiple myeloma, for example, longitudinal scRNA-seq identified peptidylprolyl isomerase A (PPIA) as a transcriptomic signature of resistance, but its functional validation as a therapeutic target requires confirmation at the protein level." (PMID 41550661, 2025).